CDH17 (cadherin 17)
Diseases named in the same sentence as CDH17 in open-access papers (continued):
Sharing a sentence is not in itself a finding about the gene and the disease.
ovarian carcinoma (4 papers, 2017 to 2025). A malignant neoplasm originating from the surface ovarian epithelium. "Regarding other tumors, up-regulation of CDH17 was observed in advanced stages of epithelial ovarian cancer and associated with poor prognosis." (PMID 31324051, 2019). "Indeed, high expression of CDH17 in this subtype of ovarian cancer can be readily observed in the Human Protein Atlas." (PMID 31324051, 2019). "In addition, the prognosis of gastric and ovarian cancer patients with tumors expressing cadherin-17 is significantly worse than that of patients whose tumors do not express cadherin-17." (PMID 28197418, 2017). "Interestingly, in some ovarian cancers, overexpression of CDH17 has been reported, suggesting that both cadherins might coexist in some cancer tissues." (PMID 31324051, 2019). "Silencing of α2 or αIIb inhibited the adhesive capacity of the ovarian cancer cells in the presence of CDH6 and CDH17 peptides." (PMID 33715292, 2021). "CDH17 has not been previously reported in Mullerian‐related tumors, although a clear overexpression of CDH17 can be observed in the mucinous subtype of ovarian cancer at the tissue level in the Human Protein Atlas database." (PMID 33715292, 2021).
pancreatic ductal adenocarcinoma (4 papers, 2019 to 2025). An infiltrating adenocarcinoma that arises from the epithelial cells of the pancreas. "Given the potent antitumour effects of OMVs, this study systematically evaluated the efficacy and mechanistic basis of modified OMVs derived from engineered E. coli MG1655 in CDH17‐positive colorectal (CRC) and pancreatic ductal adenocarcinoma (PDAC) models." (PMID 40240911, 2025).
colon adenocarcinoma (3 papers, 2020 to 2024). "While comparing the usefulness of CDH17 in immunohistochemical diagnostics in gastrointestinal carcinomas with CDX2, it has been observed that almost all colon adenocarcinomas (99%) are CDH17-positive/CDX2-positive." (PMID 35055034, 2022).
liver cancer (3 papers, 2013 to 2022). An epithelial or non-epithelial malignant neoplasm that arises from the liver. "Antibody against CDH17 plus cisplatin could control liver cancer progression." (PMID 36435809, 2022). "This indicates that CDH17 may be crucial in the tumorigenesis of gastric and liver cancer." (PMID 23554857, 2013). "The corresponding genes of middle-stage CNV events including MYC, CNBD1, HEY1, RUNX1T1, CDH17, high expression of HEY1 gene promotes self-renewal of tumor stem cells, especially in liver cancer." (PMID 34453042, 2021).
lung adenocarcinoma (3 papers, 2018 to 2024). A carcinoma that arises from the lung and is characterized by the presence of malignant glandular epithelial cells. "CDH17 had been found to be characterized by single-nucleotide polymorphisms in lung adenocarcinoma in a proteomic study." (PMID 35903696, 2022). "While the role of CDH17 in lung adenocarcinoma is not well understood, our IHC findings are consistent with results obtained via tissue microarrays targeting CDH17 in patients diagnosed with metastatic colorectal adenocarcinoma." (PMID 29899869, 2018). "These networks contain human-derived N-glycoproteins with an already-established linkage/role in lung adenocarcinoma signaling (e.g., CD44, CD147) and proteins whose relevance to the biology of lung adenocarcinoma is less clear (e.g., CDH17)." (PMID 29899869, 2018). "Hence, CDH17 depicted in the tumor metastasis network may be added to a cytokeratin panel for better classification of the metastatic human lung adenocarcinoma." (PMID 29899869, 2018). "The mechanism of action of CDH17 in lung adenocarcinoma has not been reported, but its relationship with lung intestinal adenocarcinoma and tumor lung metastasis has been confirmed." (PMID 35903696, 2022). "An intense parenchymal CDH17 staining was observed in human lung adenocarcinoma tissue, and CDH17 was absent in the normal adjacent tissue, which agrees with the corresponding LC-MS data obtained using TCSG." (PMID 29899869, 2018). "In comparison, SATB2 and CK20 showed higher specificity, with expression in 5% and 10% of mucinous primary lung adenocarcinomas and both in 0% of TTF-1-negative non-mucinous primary lung adenocarcinomas (25–50% and 5–16%, respectively, for GPA33/CDX2/CDH17)." (PMID 37349623, 2024).
melanoma (3 papers, 2017 to 2021). A malignant, usually aggressive tumor composed of atypical, neoplastic melanocytes. "Previously, we described the capacity of CDH17 and CDH5 (VE‐cadherin) to promote liver and lung metastasis, by interacting with α2β1 integrin via their internal RGD motif, in different tumors (colorectal, melanoma, and breast cancer)." (PMID 33715292, 2021).
pancreatic adenocarcinoma (3 papers, 2020 to 2025). "Cadherin-17 (CDH17) is a calcium-dependent cell adhesion protein that is overexpressed in several adenocarcinomas, including gastric, colorectal, and pancreatic adenocarcinoma." (PMID 38625402, 2024).
asthma (2 papers, 2020 to 2022). "Additionally, research on isocyanate-induced asthma has correlated a calcium-dependent cell adhesion gene, CDH17, with isocyanate asthma risk." (PMID 32973864, 2020).
colorectal neoplasm (2 papers, 2024 to 2025). A benign or malignant neoplasm that affects the colon or rectum. "CDH17 immunopositivity has been commonly reported in CRC, and the positive rates were as high as > 95% in colorectal neoplasm." (PMID 39617741, 2024).
gastrointestinal carcinoma (2 papers, 2022 to 2025). "Cadherin 17 is a useful biomarker of adenocarcinomas with intestinal phenotype and recently reported as an ideal target for chimeric antigen receptor T-cells (CAR-T) therapy for gastrointestinal carcinoma." (PMID 39164422, 2025).
metastatic carcinoma (2 papers, 2020 to 2025). A carcinoma which has spread from the original site of growth to another anatomic site. "Interestingly, CDH5, CDH17, and L1CAM share their involvement in several metastatic cancers, which could be related to the pairwise sequence alignment found near the RGD motif for the combinations CDH17/L1CAM and CDH17/CDH5 (its second RGD motif)." (PMID 41039222, 2025).
Alzheimer disease (1 paper, 2018). A progressive, neurodegenerative disease characterized by loss of function and death of nerve cells in several areas of the brain leading to loss of cognitive function such as memory and language. "PANTHER pathways analysis of differentially expressed proteins revealed overrepresentation of Wnt signaling pathway (CDH1, CSNK2A2, GNA11, CTBP2, CDH17, SMARCE1, p-value 0.02), followed by Alzheimer disease-presenilin pathway (MMP8, MMP9, MLLT4, CDH1, P-value 0.04)." (PMID 29515771, 2018).
cerebral cavernous malformation (1 paper, 2012). A disorder characterized by malformations in the structure of the capillaries in the brain. "We observed that “Generic Binding Proteins” were enriched in the MapsloBTlo region of the graph and corresponded to weakly connected genes; examples at the lowest end (Maps = 1, BT = 0) include CCM2 (cerebral cavernous malformation 2), CD96, and CDH17 (liver-intestine cadherin)." (PMID 22548703, 2012).
chronic atrophic gastritis (1 paper, 2007). Atrophic gastritis that is persistent and long-standing. "Expression levels of li-cadherin (cdh17) were reported to be significantly higher in chronic atrophic gastritis with IM than in GC, and lower in poorly differentiated tumors than in well- and moderately differentiated tumors, as well as showing increased expression levels in lymph node metastasis." (PMID 19412438, 2007).
colitis (1 paper, 2022). Inflammation of the colon. "In a Cdh17 knockout (KO) mouse model, loss of cadherin-17 has been shown to result in increased permeability and susceptibility to chemically induced colitis and to enhanced tumour formation and progression." (PMID 36612154, 2022).
colonic carcinomas (1 paper, 2017). "Lin's study reported that the rate of CDH17-positivity was 98% (123/125) in colonic carcinomas." (PMID 28969003, 2017).
dysplasia (1 paper, 2025). A usually neoplastic transformation of the cell, associated with altered architectural tissue patterns. "In dysplasias, ten of 11 (91%) cases were positive for CDH17 and 6 of 11 (55%) were positive for CLDN18." (PMID 39164422, 2025).
gastric adenoma (1 paper, 2004). A neoplastic polyp that arises from the stomach. "On the one hand, the expression profiles of CDH17, DEFA5 and other CDX2 regulated genes may constitute specific tumour markers for a distinct subgroup of gastric adenomas with a progressive nature." (PMID 14710232, 2004).
intestinal cancer (1 paper, 2025). "Loss of CDH17 resulted in a marked down-regulation of the intestinal cancer stem cell (CSC) marker LGR5, leading to the inhibition of Wnt/β-catenin signaling, suppression of pluripotency genes such as MYC, and a subsequent reduction in stemness properties." (PMID 40595509, 2025).
invasive carcinoma (1 paper, 2025). A carcinoma that is not confined to the epithelium, and has spread to the surrounding stroma. "Three of 25 (12%) CD-SBNs (1 conventional type invasive carcinoma and 2 conventional type dysplasias; 1 dysplasia was adjacent to SATB2 positive invasive carcinoma) were SATB2 positive and all SATB2-positive CD-SBNs showed CDH17 expression, whereas no CLDN18 expression was identified." (PMID 39164422, 2025).
mucinous adenocarcinoma of the lung (1 paper, 2023). "Indeed, sensitivity to bortezomib was observed in mucinous adenocarcinoma of the lung, and we previously found that HGM CRC is preferentially sensitive to pevonedistat in models with low or absent expression of cadherin 17 (CDH17), a differentiation marker." (PMID 36816936, 2023).
Pneumocystis infection (1 paper, 2010). "Dexamethasone treatment increased Cdh17 expression by 7.15 fold, but Pneumocystis infection not only reversed this effect but also decreased its expression by 1.61 fold." (PMID 20377877, 2010).
renal carcinoma (1 paper, 2021). A carcinoma arising from the epithelium of the renal parenchyma or the renal pelvis. "Of note, knocking down CDH17 and CDH6 caused similar effects in reducing the pro‐metastatic properties of ovarian and renal cancer cells, likely through the direct interaction of CDH17 with α2β1 integrin." (PMID 33715292, 2021). "We have now investigated the expression levels and different molecular interactions of CDH6, CDH17, αIIbβ3, and α2β1 integrins in ovarian and renal cancer." (PMID 33715292, 2021).
small bowel carcinoma (1 paper, 2025). "By finding retained CDH17 expression and frequent CLDN18 expression, our study indicates the possibility of widened treatment options in CD-associated small bowel carcinoma patients." (PMID 39164422, 2025).
viral infection (1 paper, 2022). "However, there is a paucity of studies on the relationship between Cadherin 17 and viral infection." (PMID 36152751, 2022).
viral myocarditis (1 paper, 2022). Myocarditis that is caused by an infection with a viral agent. "The proteins ICAM1 (M3WBF1_FELCA) and CDH17 (M3WMR7_FELCA) were upregulated, while ITGAL (M3 WC52_FELCA) and ITGAE (M3W8N0_FELCA) were downregulated in the viral myocarditis pathway." (PMID 36290246, 2022).
tumor (67 papers, 2004 to 2026). "Clinically, current evidence suggests associations between CDH17 expression and tumour progression, particularly in males, as well as improved overall survival in patients with low CDH17 expression." (PMID 41155133, 2025). "These design differences likely account for the result’s divergences, with our study confirming a significant association between high CDH17 expression and histological type, grade, and Bd in the tumor core, as well as advanced stage in tumor emboli." (PMID 40725206, 2025). "Still, due to the loss of cell polarity in tumor cells, CDH17 is distributed across the surface of tumor cells, which provides a good opportunity for targeted therapy." (PMID 40721409, 2025). "The authors found that high CDH17 expression in tumor tissue was associated with advanced tumor staging and distant metastasis." (PMID 40725206, 2025). "Nonetheless, our study analyzes the CDH17 immunohistochemical expression in tumor emboli, showing a statistically significant association with T stage." (PMID 40725206, 2025). "Our data showed that patients with high levels of CDH17 immunohistochemical expression in tumor emboli have an approximately twofold risk of death compared to those with low expression, adjusted for other covariates." (PMID 40725206, 2025). "Elevated CDH17 expression has been linked to tumor progression, invasion, metastasis, and poor prognosis in GC patients." (PMID 40487639, 2025). "CDH17 immunohistochemical expression in the tumor invasive front was significantly associated only with PDCs (p = 0.018), which suggests that low CDH17 levels are considerably more correlated with a score of Pdc2." (PMID 40725206, 2025). "Nonetheless, we demonstrate that patients with high levels of CDH17 immunohistochemical expression in tumor emboli have an approximately twofold risk of death compared to those with low expression, adjusted for other covariates." (PMID 40725206, 2025). "An exploratory sex-stratified analysis revealed that CDH17 expression was significantly associated with cancer progression in males but not in females, hinting at a possible sex-dependent role of CDH17 in tumour biology." (PMID 41155133, 2025). "At the same time, we also found that the CDH17 monoclonal antibody had better binding activity than the GUCY2C monoclonal antibody, which was probably caused by the higher expression level of CDH17 on tumor cells than GUCY2C." (PMID 40721409, 2025). "CDH17 immunohistochemical expression in the tumor core was statistically significantly associated with EPNI (p = 0.041) and Bd (p = 0.037)." (PMID 40725206, 2025). "Our findings revealed that a higher CDH17 M Score was associated with advanced tumor burden and poorer survival outcomes." (PMID 39617741, 2024). "First, we identified hypermethylation of CDH17 as a predictor of high risk of recurrence in these patients, suggestive of a role for this factor as a tumour suppressor in the early stage CC." (PMID 36612154, 2022). "In many of these cancers, CDH17 expression is associated with tumor stage or poor survival of patients." (PMID 31324051, 2019). "Furthermore, high CDH17 levels in tumor core/tumor emboli were significantly associated with grading (p = 0.004/p = 0.040), especially with a low-grade of differentiation." (PMID 40725206, 2025). "Hence, we noticed new associations among CDH17 immunohistochemical expression in the tumor core and EPNI and Bd, respectively." (PMID 40725206, 2025). "Additionally, a strong statistical association was found between CDH17 immunohistochemical expression in tumor emboli and T stage (p = 0.046), suggesting that high CDH17 levels in tumor emboli are more associated with T stage 3." (PMID 40725206, 2025). "Proposed hypotheses to explain the male-specific association with CDH17 expression include hormonal differences (androgens), sex chromosome-linked genes, as well as potential immunologic variations that can influence tumour microenvironment and progression." (PMID 41155133, 2025).
tumor (continued). "CDH17, a liver-intestine cadherin, is an adhesion molecule implicated in tumor progression." (PMID 40725206, 2025). "A significant statistical association was found between CDH17 immunohistochemical expression in tumor core/tumor emboli/lymph node metastasis and histological type (p = 0.001/p = 0.023/p = 0.022), with high CDH17 levels being more associated with adenocarcinoma NOS cases." (PMID 40725206, 2025). "Hence, CDH17 represented a class of previously unappreciated tumor-associated antigens in gastrointestinal tract tumors that was negatively expressed in healthy tissues." (PMID 38608841, 2024). "Increased CDH17 M Score was associated with advanced tumor staging and poor survival outcomes using an automated IHC system integrated with a digital image analysis software, highlighting CDH17 could serve as an independent prognostic marker for CRC patients." (PMID 39617741, 2024). "CDH17 also holds potential prognostic significance, although its clinical relevance varies according to molecular context and tumor differentiation status, emphasizing the need for integrative biomarker assessment." (PMID 41928253, 2026). "CDH17 regulates cell–cell adhesion, modulates key signaling pathways, and interacts with the tumor microenvironment, collectively influencing proliferation, invasion, metastasis, therapeutic resistance, and immune evasion." (PMID 41928253, 2026). "The selected predictors used in the model were CDH17 immunohistochemical expression in tumor emboli, histological type, LVI, EMVI, EPNI, and prognosis stage group." (PMID 40725206, 2025). "CDH17-CAR-NK cells also exhibit potent in vivo anti-tumor effects in cancer cell-derived xenograft and patient-derived xenograft mouse models." (PMID 40487639, 2025). "Strikingly, CDH17-CAR-NK92 cells exhibited markedly higher tumor accumulation at 48 and 72 h, underscoring their targeted localization advantage." (PMID 40487639, 2025). "In contrast, our study analyzed CDH17 immunoexpression in multiple histological regions—tumor core, invasive front, lymphovascular emboli, and lymph node metastases—in 84 CRC cases selected for the presence of lymphovascular invasion." (PMID 40725206, 2025). "In conclusion, CDH17-targeting CAR-NK92 cells exhibit robust anti-tumor activity in multiple GI cancers, as demonstrated in both CDX and PDX models." (PMID 40487639, 2025). "In vivo data shows that KD of CDH17 in xenograft models reduced tumour growth by 80–95%, while antibody-based inhibition with Lic5 led to over 50% tumour reduction and synergized with cisplatin to achieve almost complete suppression in HCC models." (PMID 41155133, 2025). "High levels of CDH17 immunohistochemical expression in tumor emboli were confirmed as an independent prognostic biomarker, being correlated with a poor outcome and doubling the risk of death." (PMID 40725206, 2025). "To further confirm that CDH17 nanobody‐engineered OMVs enhance tumour selectivity and minimise off‐target accumulation, we employed the more sensitive near‐infrared (NIR)‐II imaging system using ICG‐conjugated OMVs." (PMID 40240911, 2025). "Our investigation demonstrates the potent anti-tumor activity of CDH17-CAR-NK cells against CDX and PDX mouse models." (PMID 40487639, 2025). "While CV1 alone did not markedly reduce tumor size compared to the PBS control, its addition significantly enhanced the anti-tumor effects and improved mouse survival of CDH17-CAR-NK92 cells compared with CDH17-CAR-NK92 or CV1 monotherapy." (PMID 40487639, 2025). "The lipid peroxidation products in tumor cells were significantly increased after BsADC treatment and were significantly more than those in cells treated with CDH17-ADC or GUCY2C-ADC." (PMID 40721409, 2025). "CDH17 knockdown markedly increased the growth of tumor xenografts and significantly enhanced the inhibitory effect of cisplatin on tumor growth." (PMID 39994505, 2025).